ZKSCAN3 (zinc finger with KRAB and SCAN domains 3)
Diseases named in the same sentence as ZKSCAN3 in open-access papers (continued):
Sharing a sentence is not in itself a finding about the gene and the disease.
ZKSCAN3 also shares sentences with these, for which no sentence is quoted: adenocarcinoma (2 papers); lymph node metastases (2); glioma (1); hyperplastic polyp (1); papillary urothelial neoplasm (1); prostatic intraepithelial neoplasia (1); psychiatric disorder (1); type 2 diabetes mellitus (1); ureteral tumors (1); urothelial carcinoma (1).